HCN1 (hyperpolarization activated cyclic nucleotide gated potassium channel 1)
Diseases named in the same sentence as HCN1 in open-access papers (continued):
Sharing a sentence is not in itself a finding about the gene and the disease.
epilepsy (continued). "Our results suggest that ablation of X11/X11L induces aberrant HCN1 distribution and function along with epilepsy." (PMID 23034178, 2012). "In a pilocarpine-induced epilepsy model, dendritic HCN1 and HCN2 channels were initially downregulated but later increased during the chronic phase, indicating that regional Ih density may influence seizure susceptibility or resistance." (PMID 41318467, 2025). "As proposed for the p.(Met305Leu) HCN1 variant, blocking the aberrant p.(Met374Leu) HCN2/HCN1 leaking channels could be a therapeutical strategy to prevent epilepsy." (PMID 40468825, 2025). "This deficit in HCN1 function leads to hyperexcitability and may contribute to the development of epilepsy, further exacerbating Aβ production." (PMID 38999445, 2024). "In humans, HCN1 has been proved to be involved in epilepsy diseases, including genetic generalized epilepsies, epilepsy with febrile seizures plus, epileptic encephalopathy, early infantile epileptic encephalopathy, catastrophic epilepsies, and so on." (PMID 39765460, 2024). "Furthermore, the evidence for variants in HCN1, HCN2, and HCN4 in human epilepsy has rapidly grown in recent years." (PMID 39361439, 2024). "What are the potential advantages of HCN1 as a therapeutic target for epilepsy?" (PMID 37366350, 2023). "Although HCN1 is just one of several hundred neuronal genes that contain the binding sequence and respond to the ODNs, it is still possible that reversing the downregulation of HCN1 and the Ih current may be beneficial to epilepsy treatment." (PMID 37366350, 2023). "A specific HCN1 blocker is also needed to explore the role of HCN1 channels in epilepsy therapy." (PMID 37366350, 2023). "In addition, HCN1 expression increased in the stratum pyramidale (SP) layer, where the soma of pyramid neuron is located, implying that the original distribution of HCN1 changed in the course of epilepsy." (PMID 37366350, 2023). "Interestingly, the blockage of HCN1-mediated Ih current in the pyramidal, cortical, and thalamic neurons contributes to epilepsy, whereas blockers of HCN3- and HCN4-mediated currents suppress seizures." (PMID 35663267, 2022). "Since the only HCN subtype expressed in PV+ interneuron terminals is HCN1, diminished GABAergic input onto excitatory neurons as a result of HCN1 protein dysfunction could contribute to excitation/inhibition imbalance and epilepsy." (PMID 35972069, 2022). "Activation of HCN1 current may contribute to the overall reduction of neuronal hyperactivity in epilepsy with CBD treatment, similar to the reduced neuronal firing observed in CA1 pyramidal neurons resulting from lamotrigine stimulated Ih." (PMID 35465092, 2022). "Initially, the clinical manifestation of HCN1-related epilepsy was termed Dravet syndrome." (PMID 35845605, 2022). "This is supported by data from experimental animal models of global HCN1 knockout, characterized by a predisposition to the development of epilepsy, but without spontaneous seizures." (PMID 25805968, 2015). "Studies in rat models have also shown that Hcn1 has a key role in epilepsy." (PMID 25970616, 2015). "Hence, specific HCN1 blockers should be tested before or after spontaneous seizure onset to accurately evaluate the involvement of HCN1 channels in epileptogenesis, and their suitability as a target for epilepsy therapy." (PMID 37366350, 2023). "To date, no genetic mutations in HCN1 ion channels in the absence epilepsy have been identified." (PMID 36766503, 2023). "Besides epilepsy, intellectual disability, behavioral disturbances, autistic features, polyphagia, motor delay, ADHD, truncal ataxia, language delay, and microcephaly can be noticed in the cases with HCN1 pathogenic variants." (PMID 35663267, 2022).
epilepsy (continued). "However, phenotypes and pathogenesis of HCN1-related epilepsy are still poorly understood." (PMID 35845605, 2022). "HCN1 channels contribute to control of excitability in pyramidal cell dendrites in the hippocampus and entorhinal cortex by attenuating excitatory input, and mice lacking HCN1 channels are susceptible to epilepsy." (PMID 33813634, 2021). "Recent gene discoveries such as GABRB3, GRIN2A, HCN1, KCNA2, and KCNH1 support the channelopathy hypothesis, and genes that encode ion channels certainly represent the largest class of disease-causing genes in epilepsy." (PMID 26302787, 2015). "Thus, altered expression of HCN channels or Ih is a phenomenon regularly observed in models of experimental epilepsy, and even in human epilepsy, and altered interaction of HCN1 with TRIP8b could be a critical mechanism contributing to this phenomen." (PMID 22363812, 2012). "In epilepsy/TLE models, the expression and surface localization of HCN1 in the dendrites of CA1 pyramidal neurons decrease rapidly, and the gating of Ih shifts toward more negative potentials (referred to as “acquired dendritic channelopathy”)." (PMID 41603014, 2026). "Our study was initiated in 2014, following the discovery of HCN1's role in epilepsy, which sparked our interest in investigating the involvement of HCN3 in epilepsy due to its similarities to HCN channel subtypes." (PMID 39361439, 2024). "Dendritic HCN1 and HCN2 channels were found to be downregulated in a pilocarpine model of epilepsy, while in the chronic period, expression of these channels increased." (PMID 37293624, 2023). "Other disorders with relatively high rates of ASD features alongside epileptic encephalopathy include HCN1-related epilepsy (67%) and SIK1-related epilepsy (50%)." (PMID 28649286, 2017). "Seizures provoke a prolonged remodeling of HCN1 and HCN2 expression, supporting the presence of a transcriptional channelopathy involving HCN channels which contributes to the development of epilepsy." (PMID 25805968, 2015). "HCN1 variants are associated with a broader clinical spectrum, including developmental and epileptic encephalopathy (DEE) (DEE24; # 615871), epilepsy without intellectual disability (ID), and ID without seizures." (PMID 40468825, 2025). "Hyperpolarization-activated cyclic nucleotide-gated channel 1 (HCN1), important for regulating neuronal activity, has been studied extensively in epilepsy research but not much in AD research." (PMID 34862388, 2021). "Thus, the clinical effectiveness of ZD7288 and ivabradine is not sufficient to prove the benefits of blocking HCN1 channels for epilepsy treatment." (PMID 37366350, 2023). "Visual deficits have not previously been reported in HCN1 epilepsies." (PMID 35359652, 2022). "Interestingly, HCN1 exon deletions have been previously reported in patients with autism spectrum disorders, but without epilepsy." (PMID 25805968, 2015).
depression (15 papers, 2019 to 2025). "The aberrant HCN1 protein subcellular distribution along the somatodendritic axis of CA1 neurons is linked to pathogenic events in the animal models of depression and temporal lobe epilepsy." (PMID 35840797, 2022). "Increases in HCN1 protein expression are thus implicated in the development of depression and a treatment-related reduction of HCN1 protein expression is associated with resilience to later chronic stress exposure." (PMID 34899408, 2021). "Genome-wide association studies (GWAS) have not previously implicated HCN1 in alcohol use disorders, but other GWAS studies have found that HCN1 is associated conditions like schizophrenia and depression, which are known to be comorbid with AUDs." (PMID 33105624, 2020). "Of the four isoforms, HCN1 channels have been specifically implicated in depression." (PMID 37234718, 2023). "However, it is noteworthy to highlight the upregulation of the hyperpolarization-activated cyclic nucleotide-gated channel 1 (HCN1), an ion channel associated with stress-related disorders, including schizophrenia and depression (Shah, 2012; C. S. Kim and Johnston, 2018)." (PMID 39147579, 2024). "Uniquely, the decrease in CNPase and synaptophysin in the white matter mediate an impairment of synaptic potentiation and in anxiety and depression, alongside the upregulation of HCN1 and downregulation of KCNQ3 in the amygdala." (PMID 39851502, 2025). "Intriguingly, the role of HCN2 and HCN4 in major depressive disorder is less straightforward than HCN1." (PMID 39434909, 2024). "HCN1−/− mice show impaired motor learning but enhanced spatial learning and memory and enhanced resistance to depression." (PMID 39434909, 2024). "Physiological experiments also point to HCN1 channel activity as an important driver of pathology in depression." (PMID 37234718, 2023). "There is evidence of the role of HCN channels, in particular HCN1, in depression and antidepressant effects." (PMID 36766503, 2023). "A reduction of HCN1 protein expression in the dorsal CA1 region (about 30% of the dorsal CA1 region) before the CUS-induced onset of depression and anxiety is sufficient to provide resilient effects to CUS." (PMID 35840797, 2022). "At the behavioural level, TRIP8b expression in CA1 neurons has been linked to major depressive disorder (MDD) and human MDD patients and animal models of chronic stress exhibit higher expression of hippocampal HCN1." (PMID 35795651, 2022). "Multiple aspects of these processes are implicated in the development of anxiety and depression in CCH, including aberrant GABA and glutamate signaling, reduced BDNF, impaired synaptic potentiation, changes in synaptophysin, serotonin, and HCN1, as well as reduced dopamine and KCNQ3 activity." (PMID 39851502, 2025). "Inhibition of HCN1 channels has been suggested as a key therapeutic target for depression." (PMID 39434909, 2024). "This study aimed to investigate whether the maternal methyl-enriched diet (MED), which affects DNA methylation, can alter DNMT1, HCN1, and TH gene expression and modify absence seizures and comorbid depression in WAG/Rij offspring." (PMID 36766503, 2023). "While the picture is not clear for HCN2 channels, these data strongly support the idea that HCN1 channel inhibition may be an effective therapeutic approach to treat depression." (PMID 37234718, 2023). "There are no data concerning the expression of HCN1 channels in the hippocampus in a genetic epilepsy-associated depression-like comorbidity and its correction by antidepressant treatment." (PMID 36766503, 2023). "Furthermore, the function and expression of HCN1 channels are changed during the development of depression and a reduction of HCN1 protein expression may affect the resilience to chronic stress." (PMID 37450922, 2024).
depression (continued). "This means that targeting the expression of HCN1 ion channels in the somatosensory cortex and the mesolimbic dopaminergic system could be a potential new approach for treating absence epilepsy and comorbid depression in the WAG/Rij model." (PMID 36766503, 2023). "The reduced expression of the HCN1 ion channel in the somatosensory cortex (SSC) and mesolimbic dopamine deficiency are thought to be associated with the genesis of spike-wave discharges (SWDs) and comorbid depression in the WAG/Rij rat model of absence epilepsy." (PMID 36766503, 2023). "HCN1 and HCN2 were reported to be highly expressed in brain regions known to be involved in the pathophysiology of major depression, namely prefrontal cortex, hippocampus, ventral tegmental area (VTA) and nucleus accumbens (NAc)." (PMID 34858192, 2021). "Similarly, genetic ablation of Trip8b, an auxiliary protein that regulates HCN1 and HCN2 expression, also increases resistance to depression." (PMID 39434909, 2024). "HCN1 protein expression was increased in the dorsal CA1 region of the hippocampus following chronic unpredictable stress (CUS), but a reduction in HCN1 expression before CUS-induced depression provided a resilient effect." (PMID 36766503, 2023). "Overall, the inhibition of HCN1, which can alleviate PTSD-like behavior of rats by relieving depression and improving learning ability, may be related to the upregulated BDNF-mTOR signaling pathways and synaptic transmission." (PMID 32198387, 2020). "From the data of this study, we found that decreasing the expression of HCN1 in the animal model of PTSD alleviates PTSD-like symptoms, reducing depression-like symptoms and improving spatial learning ability followed by an upregulation of BDNF–mTOR signaling pathways in the PFC and Hip." (PMID 32198387, 2020). "Although the hypothalamus is related to some aspects of depression and dopaminergic projections from the ventral tegmental area to the nucleus accumbens pass through the hypothalamus, no changes in the DNMT1 and HCN1 gene expression have been revealed." (PMID 36766503, 2023).
Epileptic encephalopathy (14 papers, 2015 to 2024). A condition in which epileptiform abnormalities are believed to contribute to the progressive disturbance in cerebral function. "The phenotypic spectrum associated with HCN1 variants ranges from neonatal developmental and epileptic encephalopathy to idiopathic generalized epilepsy." (PMID 37353494, 2023). "Variants in HCN1 are associated with a range of epilepsy syndromes including developmental and epileptic encephalopathies." (PMID 35359652, 2022). "Recently, de novo missense mutations in the HCN1 gene were identified in patients with early infantile epileptic encephalopathy-24." (PMID 25970616, 2015). "HCN1/2 are implicated in early infantile epileptic encephalopathy and absence seizures." (PMID 39569070, 2024). "Furthermore, the deletion of HCN1 in mice resulted in greater seizure susceptibility and loss of function mutations in HCN1 have been recently reported causing severe neonatal epileptic encephalopathies." (PMID 32676011, 2020). "Of new genetic models, recent data showed that levetiracetam significantly reduced ECoG spike frequency medication in a mouse model of potassium/sodium hyperpolarization-activated cyclic nucleotide-gated channel 1 (HCN1) developmental and epileptic encephalopathy." (PMID 38776036, 2024). "In addition, variants in HCN1, another member of the HCN family, were detected in patients with epileptic encephalopathy and clinical features of Dravet syndrome, intellectual disability, and autistic features." (PMID 31323926, 2019).
schizophrenia (9 papers, 2019 to 2024). A major psychotic disorder characterized by abnormalities in the perception or expression of reality. "HCN1, a hyperpolarization-activated cation channel involved in native pacemaker currents in neurons and the heart, has been significantly associated with schizophrenia and autism." (PMID 33462189, 2021). "Gene HCN1 polymorphism (rs1501357) has been proposed to be one of the candidate risk genes for schizophrenia in the second report of the Psychiatric Genomics Consortium–Schizophrenia Workgroup." (PMID 35987754, 2022). "HCN1 was firstly identified by the Psychiatric Genomics Consortium–Schizophrenia Workgroup (PGC–SCZ) in their second report (PGC2)." (PMID 35987754, 2022). "Our results further supported the association between HCN1 gene polymorphism at rs1501357 and an impairment of working memory in schizophrenia patients, suggesting that HCN1 gene and HCN channel may be the genetic mechanisms of cognitive impairment in schizophrenia." (PMID 35987754, 2022).
Anxiety (7 papers, 2018 to 2025). Intense feelings of nervousness, tension, or panic often arise in response to interpersonal stresses. "The role of other perioperative factors associated with the SIRT3 and HCN1 channels in the mPFC in postoperative anxiety behavior should be explored in the future studies." (PMID 35372451, 2022). "Ketamine affects HCN1 expression in the prefrontal cortex to alleviate PTSD-associated anxiety symptoms." (PMID 35372451, 2022). "Therefore, the relationship of SIRT3 on SOD2 acetylation, MMP reduction, and related HCN1 channel dysfunction in postoperative anxiety-like behavior and its underlying neuroprotective mechanism were studied in this research work." (PMID 35372451, 2022). "Based on this background, the present study hypothesized that changes in synaptic ultrastructure, which could be induced by a reduction of BDNF due to an increase in HCN1 expression in the Hip and NAc, might be associated with ethanol withdrawal-induced anxiety." (PMID 29896126, 2018). "Our findings that NQTP is a selective inhibitor of HCN1 channels contributes to the understanding of the mode of action of quetiapine for the treatment of neuropsychiatric disorders such as anxiety, major mood disorder, and others." (PMID 39434909, 2024). "We found that SIRT3 level reduced and HCN1 expression level increased in mice medial prefrontal cortex (mPFC) as well as anxiety like behavior postoperatively." (PMID 35372451, 2022). "These consequences showed that HCN1 blocker ZD7288 attenuated anesthesia/surgery induced anxiety emotion in mice." (PMID 35372451, 2022). "This study was conducted to examine the effects of SIRT3 on anxiety-like behavior induced by anesthesia/surgery in mice and assess the role of HCN1 channels." (PMID 35372451, 2022). "The protective effects of SIRT3 on anxiety-like behavior appeared to be related to HCN1 channel function." (PMID 35372451, 2022). "Several studies have reported that the HCN1 channel is related to anxiety in different disease models, but no studies have evaluated HCN1 channels in anesthesia/surgery-induced anxiety-like behavior and the dependence of HCN1 channel on SIRT3." (PMID 35372451, 2022). "This as well as the shorter distances traveled in the center square and in total distance in the OFT demonstrate that the activation of HCN1 can lead to severe anxiety-like behavior and reduced exploration ability compared with the SPS&S + Vehicle group." (PMID 32198387, 2020). "This manipulation not only reproduced the cognitive deficits observed in SPS-CORT mice but also induced anxiety-like behavior, suggesting that elevated HCN1 activity contributes to both cognitive and emotional dysfunction, depending on its magnitude or anatomical context." (PMID 40671804, 2025). "HCN1 overexpression in dorsal CA1 of SPS mice not only reproduced the cognitive deficits observed in the SPS + post-CORT group but also induced anxiety-like behaviors, suggesting that heightened HCN1 activity contributes to stress-induced behavioral impairments." (PMID 40671804, 2025). "Recent studies have indicated that HCN1 channel activity induces anxiety in the hippocampus." (PMID 35372451, 2022). "In our study, the HCN1 inhibitor ZD7288 could prevent anesthesia/surgery-induced anxiety-like behavior, indicating the key role of the HCN1 channel." (PMID 35372451, 2022). "In addition, hyperpolarization-activated cyclic nucleotide-gated 1 (HCN1) channel is also reported involved in anxiety symptoms." (PMID 35372451, 2022). "Our results revealed that SIRT3 might have an important regulatory function in the HCN1 channel through the SOD2 acetylation-mediated mitochondrial pathway in a mouse model of postoperative anxiety." (PMID 35372451, 2022). "For example, in the hippocampus, HCN1 channel activity appears to induce anxiety." (PMID 35372451, 2022).